PYM1 (PYM1 exon junction complex associated factor)
Description:
Key regulator of the exon junction complex (EJC), a multiprotein complex that associates immediately upstream of the exon-exon junction on mRNAs and serves as a positional landmark for the intron exon structure of genes and directs post-transcriptional processes in the cytoplasm such as mRNA export, nonsense-mediated mRNA decay (NMD) or translation. Acts as an EJC disassembly factor, allowing translation-dependent EJC removal and recycling by disrupting mature EJC from spliced mRNAs. Its association with the 40S ribosomal subunit probably prevents a translation-independent disassembly of the EJC from spliced mRNAs, by restricting its activity to mRNAs that have been translated. Interferes with NMD and enhances translation of spliced mRNAs, probably by antagonizing EJC functions. May bind RNA; the relevance of RNA-binding remains unclear in vivo, RNA-binding was detected by PubMed:14968132, while PubMed:19410547 did not detect RNA-binding activity independently of the EJC.
Synonyms: PYM; WIBG
Tractability: PROTAC: ubiquitination databases record sites on it; its protein half-life has been measured.
Gene: Protein-coding gene on chromosome 12 (55,901,413 to 55,932,618, reverse strand). Ensembl gene ENSG00000170473.
Subcellular location: Cytoplasm; Nucleus, nucleolus; Nucleus, nucleoplasm
Subcellular location (Human Protein Atlas): Cytosol; Nucleoli; Nucleoplasm; Cell Junctions
Gene Ontology:
Molecular function: protein binding; ribosome binding; RNA binding
Biological process: exon-exon junction complex disassembly; nuclear-transcribed mRNA catabolic process, nonsense-mediated decay; positive regulation of translation
Cellular component: cytoplasm; cytosol; exon-exon junction complex; nucleolus; nucleoplasm
Genetic constraint (gnomAD): Loss-of-function variants: 7 observed, 21.2 expected, observed/expected ratio (o/e) 0.33, 90% interval 0.19 to 0.62. The upper end of that interval is the gene's LOEUF score, 0.62, which puts it in group 2 of 6, group 1 being the genes least tolerant of losing a copy. Missense variants: 194 observed, 256.86 expected, observed/expected ratio (o/e) 0.76, 90% interval 0.67 to 0.85. Synonymous variants: 100 observed, 102.99 expected, observed/expected ratio (o/e) 0.97, 90% interval 0.82 to 1.15.
Homologues: Orthologues: chimpanzee PYM1 (100% identical), macaque PYM1 (94% identical), dog PYM1 (93% identical), rabbit PYM1 (92% identical), pig PYM1 (90% identical), guinea pig PYM1 (89% identical), mouse Pym1 (89% identical), rat Pym1 (84% identical), tropical clawed frog pym1 (56% identical), zebrafish pym1 (50% identical), Drosophila melanogaster Pym (31% identical), Caenorhabditis elegans T20G5.9 (26% identical).
Diseases named in the same sentence as PYM1 in open-access papers:
PYM1 is named in the same sentence as 7 diseases in open-access papers, as found by Europe PMC text mining. Sharing a sentence is not in itself a finding about the gene and the disease. The quoted sentences say what the papers report.
Epstein-Barr virus infection (1 paper, 2023). An infection that is caused by Epstein-Barr virus. "Specifically, SIRT6 was enriched in thermogenesis, while PSMD14 and PSMC6 were enriched in Epstein-Barr virus infection, and NCBP2 and PYM1 were enriched in nucleocytoplasmic transport." (PMID 37958518, 2023).
viral infection (1 paper, 2023). "Intriguingly and in contrast to HCV, PYM1, along with MAGOH and UPF1, was identified as an anti-viral factor of WNV, DENV and ZIKV (who are from a different Flaviviridae genus than HCV) because knockdown of PYM1 increased viral infection and/or RNA levels in HEKs cells." (PMID 36979701, 2023).
infection (1 paper, 2020). The state of being infected such as from the introduction of a foreign agent such as serum, vaccine, antigenic substance or organism. "The authors cross-referenced this screen with proteomics data they generated for WNV-interacting proteins, identifying PYM1 as a factor that both interacts with WNV capsid proteins and suppresses infection." (PMID 32699064, 2020). "Because tethering of PYM1 to reporter mRNAs leads to NMD-induced degradation, the authors hypothesized that during the course of infection, the EJC protein RBM8A, assisted by PYM1, targets WNV RNA for NMD." (PMID 32699064, 2020).
PYM1 also shares sentences with these, for which no sentence is quoted: cancer (3 papers); tumor (2); Obesity (1); pancreatic cancer (1).